VMP1 (vacuole membrane protein 1)
Description:
Phospholipid scramblase involved in lipid homeostasis and membrane dynamics processes. Has phospholipid scramblase activity toward cholesterol and phosphatidylserine, as well as phosphatidylethanolamine and phosphatidylcholine. Required for autophagosome formation: participates in early stages of autophagosome biogenesis at the endoplasmic reticulum (ER) membrane by reequilibrating the leaflets of the ER as lipids are extracted by ATG2 (ATG2A or ATG2B) to mediate autophagosome assembly. Regulates ATP2A2 activity to control ER-isolation membrane contacts for autophagosome formation. In addition to autophagy, involved in other processes in which phospholipid scramblase activity is required. Modulates ER contacts with lipid droplets, mitochondria and endosomes. Plays an essential role in formation of cell junctions. Upon stress such as bacterial and viral infection, promotes formation of cytoplasmic vacuoles followed by cell death (By similarity). Involved in the cytoplasmic vacuolization of acinar cells during the early stage of acute pancreatitis (By similarity). (Microbial infection) Host factor required for infection by all flaviviruses tested such as Zika virus and Yellow fever virus. Probably required post-entry of the virus to facilitate the ER membrane remodeling necessary to form replication organelles.
Synonyms: TMEM49; EPG3; TANGO5
Tractability: Antibody: UniProt places it where antibodies can reach, with high confidence; UniProt predicts a signal peptide or a membrane-spanning region; its Gene Ontology location is reachable by antibodies, with medium confidence. PROTAC: ubiquitination databases record sites on it; its protein half-life has been measured.
Gene: Protein-coding gene on chromosome 17 (59,707,192 to 59,842,255, forward strand). Ensembl gene ENSG00000062716.
Subcellular location: Endoplasmic reticulum-Golgi intermediate compartment membrane; Cell membrane; Vacuole membrane; Endoplasmic reticulum membrane
Subcellular location (Human Protein Atlas): Endoplasmic reticulum; Nucleoli
Gene Ontology:
Molecular function: phospholipid scramblase activity; protein binding
Biological process: autophagosome assembly; autophagosome membrane docking; cell junction assembly; cell-cell adhesion; lipoprotein transport; Golgi organization; autophagy; plasma membrane phospholipid scrambling
Cellular component: endoplasmic reticulum; endoplasmic reticulum membrane; plasma membrane; autophagosome membrane; endoplasmic reticulum-Golgi intermediate compartment membrane; vacuolar membrane; phagophore assembly site
Genetic constraint (gnomAD): Loss-of-function variants: 4 observed, 47.59 expected, observed/expected ratio (o/e) 0.0841, 90% interval 0.04 to 0.19. The upper end of that interval is the gene's LOEUF score, 0.19, which puts it in group 1 of 6, group 1 being the genes least tolerant of losing a copy. Missense variants: 268 observed, 459.08 expected, observed/expected ratio (o/e) 0.58, 90% interval 0.53 to 0.65. Synonymous variants: 139 observed, 160.35 expected, observed/expected ratio (o/e) 0.87, 90% interval 0.75 to 1.
Homologues: Orthologues: macaque VMP1 (99% identical), pig VMP1 (97% identical), rabbit VMP1 (97% identical), chimpanzee VMP1 (96% identical), dog VMP1 (96% identical), guinea pig VMP1 (95% identical), rat Vmp1 (95% identical), mouse Vmp1 (94% identical), tropical clawed frog vmp1 (81% identical), zebrafish vmp1 (74% identical), Drosophila melanogaster Tango5 (53% identical), Caenorhabditis elegans epg-3 (46% identical), and 1 more. Paralogues in human: CYB5D2 (10% identical), PGRMC2 (10% identical), PGRMC1 (8% identical).
Diseases named in the same sentence as VMP1 in open-access papers:
VMP1 is named in the same sentence as 82 diseases in open-access papers, as found by Europe PMC text mining. Sharing a sentence is not in itself a finding about the gene and the disease. The quoted sentences say what the papers report.
breast carcinoma (19 papers, 2011 to 2025). "TNBC with increased SD on PrecontrastT1 showed a 23-fold, 13-fold, sevenfold, fivefold, and fivefold upregulation of CLEC3A, SRGN, HSPG2, KMT2D, and VMP1 respectively, and these genes are associated with poor survival in breast cancer." (PMID 37391754, 2023). "While VMP1 is related to poor patient outcomes in pancreatic cancer and breast cancer, Cdt2 is associated with more aggressive hepatocellular carcinoma, gastric cancer, and melanoma." (PMID 37629161, 2023). "Chemotherapy alters the DNA methylation pattern in leukocytes of breast cancer patients and the CpG cg16936953 in the VMP1/MIR21 gene is associated with cognitive decline in breast cancer patients." (PMID 32457596, 2020). "High expression of VMP1 associated with breast cancer specific survival (BCSS) in cohort 1 (hazard ratio (HR) = 2.31, CI 1.27–4.18) and METABRIC (HR = 1.26, CI 1.02–1.57), and also after adjusting for HER2 expression in cohort 1 (HR = 2.03, CI 1.10–3.72)." (PMID 31442252, 2019). "A particularly interesting example is a BRIP1::VMP1 fusion in the MDA-MB-361 breast carcinoma cell line." (PMID 41421967, 2025). "Other VMP1 gene fusions, where VMP1 is located in the 3' portion, have been identified in breast cancer, including CLTC/VMP1 and AC099850.1/VMP1." (PMID 38612567, 2024). "In this work, the authors described a RPS6KB1/VMP1 fusion transcript that is the product of a tandem duplication and is present in breast cancer samples." (PMID 38612567, 2024). "This investigation extends to breast cancer, colon cancer, hepatocellular carcinoma, and more, highlighting VMP1’s nuanced nature, contingent on specific tissue contexts." (PMID 38612567, 2024). "Despite the comparatively lower number of studies investigating VMP1’s role in breast cancer compared to pancreatic cancer, existing data indicate an upregulation of VMP1 expression in breast cancer." (PMID 38612567, 2024). "It was found that the tandem duplication giving rise to RPS6KB1/VMP1 in breast cancer also leads to a duplication of miR-21." (PMID 38612567, 2024). "In cluster 1, breast cancer cell markers, including Nob1, Vmp1, Crk, Ckap2, Parp14 and Mfn1, were detected among the top cluster markers." (PMID 39054536, 2024). "Of these genes, only RPS6KB1, VMP1, PPM1D and BCAS3 have been implicated in tumor development using clinical data from breast cancer patients." (PMID 34797887, 2021). "For example, miRNA-convergent fusions involving the mir-21 host gene VMP1 were found in 4.3% of all breast cancer samples analyzed at the miRNA expression level, and in more than 3% for MCM7, host gene of the mir-25-106b cluster." (PMID 28983113, 2017). "A recent study also identified the CLTC/VMP1 fusion in BT-549; our findings now demonstrate this to be a recurrent rearrangement in breast cancer." (PMID 23637631, 2013). "However, the changes of VMP1/MIR21 mRNA after paclitaxel treatment were inversely correlated with the respective paclitaxel IC50 concentrations in the detected breast cancer cells." (PMID 29392887, 2018). "On the other hand, further studies are still needed to explore the role of VMP1/MIR21 in the mechanism for the paclitaxel resistance of TNBCs as miR‐21 has been shown to be a useful biomarker to predict neoadjuvant therapeutic response in breast cancer patients." (PMID 29392887, 2018). "In the breast cancer cell line MCF-7, a fusion between exon 2 of RPS6KB1 and exon 11 of VMP1 was found." (PMID 38612567, 2024).
pancreatic cancer (16 papers, 2012 to 2024). "Vacuole Membrane Protein 1 (VMP1), identified as a crucial autophagic protein induced during acute pancreatitis, has been implicated in pancreatic cancer progression." (PMID 38612567, 2024). "In pancreatic cancer, VMP1—whose expression is linked to the Kirsten Rat Sarcoma Virus (KRAS) oncogene—significantly contributes to disease promotion, progression, and chemotherapy resistance." (PMID 38612567, 2024). "VMP1, previously thought to be a pancreatitis-associated protein, has recently been demonstrated to promote glioma development and Kras-mediated pancreatic cancer initiation by regulating cellular autophagy." (PMID 37035172, 2023). "In previous studies, we found that VMP1 expression is induced by mutated KRAS in pancreatic tumor cells." (PMID 32655498, 2020). "Moreover, higher expression levels of VMP1 are associated with poorly differentiated pancreatic cancer in human specimens." (PMID 38612567, 2024). "Notably, the G12D mutation of the KRAS oncogene, a pivotal driver in pancreatic cancer initiation, has been linked to the induction of autophagy through VMP1 expression." (PMID 38612567, 2024). "In pancreatic cancer cells, VMP1 expression is induced by mutated KRAS." (PMID 37629161, 2023). "On the one hand, research indicates that VMP1 promotes therapy resistance, similar to pancreatic cancer." (PMID 38612567, 2024). "Consistent with these molecular insights, VMP1 is found to be overexpressed in human pancreatic cancer compared to peritumoral tissues." (PMID 38612567, 2024). "The findings from these studies on pancreatic cancer underscore the promalignant role of VMP1 expression, implicating both tumoral promotion and chemotherapy resistance." (PMID 38612567, 2024). "Mechanistically, experiments performed in pancreatic cancer cell lines have shown that gemcitabine treatment induces VMP1 expression through a pathway involving the Transcription Factor E2F1 (E2F1), and EP300 ultimately triggering autophagy." (PMID 38612567, 2024). "VMP1-mediated autophagy is induced by gemcitabine through the transcription factor E2F1 in pancreatic cancer cells and by photodynamic therapy through HIF-1α in colon cancer cells." (PMID 37629161, 2023). "The expression of VMP1 in pancreatic cancer stem cells carrying the activated Kirsten rat sarcoma viral oncogene homolog (KRAS) triggers autophagy and enables therapy resistance." (PMID 37629161, 2023). "Gemcitabine, which is currently prescribed as the first-line treatment for pancreatic cancer was shown to induce VMP-1 regulated autophagy mediated apoptosis in human PDAC cells." (PMID 34830816, 2021). "VMP1 was reported to promote Kras G12D-mediated pancreatic cancer initiation and facilitate lymph node metastasis." (PMID 33604190, 2021). "Our experimental findings point at E2F1 and VMP1 as novel potential therapeutic targets in precise treatment strategies for pancreatic cancer." (PMID 32655498, 2020). "Together these data point at E2F1 as a regulatory factor modulating VMP1-mediated autophagy in human pancreatic cancer cells and integrate this degradative cellular process into the complex network of events involved in PDAC chemoresistance." (PMID 32655498, 2020). "Here we identify a new molecular pathway, mediated by VMP1, by which gemcitabine is able to trigger autophagy in human pancreatic tumor cell lines." (PMID 32655498, 2020). "In a previous work, we have identified VMP1 as a transcriptional target of oncogenic KRAS signaling pathway and demonstrated that KRAS requires VMP1 to induce and maintain basal autophagy in pancreatic tumor cells." (PMID 32655498, 2020). "KRAS activates the expression of the Vacuole Membrane Protein 1 (VMP1) to induce and maintain autophagy levels in pancreatic tumor cells." (PMID 32655498, 2020). "We demonstrated that E2F1 is able to induce autophagy in pancreatic tumor cells and regulates VMP1-mediated autophagy by a direct binding to VMP1 promoter." (PMID 32655498, 2020).
pancreatic cancer (continued). "Even, down-regulation of EP300 impaired E2F1-mediated activation of the VMP1 promoter in pancreatic tumor cells." (PMID 32655498, 2020). "In light of these clinically relevant results, it is important to review and discuss the identified functions of the VMP1 protein, which will consequently improve the interpretation of its role in pancreatic tumor progression." (PMID 27833900, 2016). "Other extracellular stimuli such as gemcitabine in pancreatic cancer cells and streptozotocine in pancreatic beta cells induce VMP1 expression and VMP1-mediated autophagy." (PMID 22550490, 2012). "Besides, several vacuole-associated proteins, such as LC3B and vacuole membrane protein 1 (VMP1), play an important role in pancreatic cancer." (PMID 39403146, 2024). "Our results point at E2F1 as a regulatory factor modulating gemcitabine induced VMP1-mediated autophagy in human pancreatic cancer cells and mechanistically integrate the autophagic degradative process into the complex network of events involved in PDAC chemoresistance." (PMID 32655498, 2020). "In order to analyze the time course effect of gemcitabine treatment on VMP1 expression we used PANC-1 and MIAPaCa-2 pancreatic tumor cells harboring a KRAS activating mutation, that are highly resistant to chemotherapy, and BxPC-3 pancreatic tumor cells that do not carry KRAS mutation." (PMID 32655498, 2020). "Besides, pancreatic tumor cells transfected with an expression vector for E2F1 induced VMP1 expression and activated autophagy." (PMID 32655498, 2020). "Besides, we demonstrated a direct binding of E2F1 on VMP1 promoter under gemcitabine treatment in pancreatic tumor cells." (PMID 32655498, 2020). "Altogether, these data show that the E2F1-EP300 activator/co-activator complex is part of the novel signaling pathway controlling the promoter activity and, consequently, the expression of the autophagy-related gene VMP1 in pancreatic tumor cells carrying oncogenic KRAS." (PMID 32655498, 2020). "In order to study the molecular mechanism that regulates VMP1 expression in the context of gemcitabine induced-autophagy in pancreatic tumor cells, a 3,005 bp sequence of the 5′ upstream region of the human gene VMP1 was amplified and cloned in the pGL3 reporter vector (pGL3.vmp1-3005)." (PMID 32655498, 2020). "In addition, we demonstrated that chloroquine, a classical inhibitor of autophagic flux, can reverse the effect of VMP1 overexpression on pancreatic cancer induced by the KRAS oncogene in a preclinical trial using our mouse model." (PMID 27833900, 2016). "Therefore, we hypothesized that VMP1 is involved in the tumor cell response to chemotherapy in pancreatic cancer cells." (PMID 32655498, 2020). "Moreover, VMP1 is highly expressed in poorly differentiated human pancreatic cancer." (PMID 32655498, 2020). "VMP1 expression is not detectable in a healthy human pancreas, but it is markedly triggered in response to pancreatitis, and pancreatic cancer." (PMID 37629161, 2023). "Although no studies have been conducted on VMP1 and ccRCC, VMP1, as an autophagy gene, plays a vital role in the development and invasion of pancreatic cancer and liver cancer." (PMID 33224313, 2020). "VMP1 is not expressed in normal pancreas, however its expression is early activated in pancreas suffering experimental diabetes mellitus, experimental and human pancreatitis, and in human pancreatic cancer cells." (PMID 32655498, 2020).
pancreatitis (16 papers, 2012 to 2025). Inflammation of the pancreas. "Autophagy is also important to prevent ER stress in acinar cells and loss of pancreatic VMP1 causes ER stress and severe pancreatitis in mice." (PMID 40577485, 2025). "VMP1 was originally characterized as a pancreatitis-associated protein; it is a multi-spanning membrane protein in the ER and is critical for autophagosome formation in mammals." (PMID 34311746, 2021). "VMP1, which was first observed in pancreatitis, encoding a multispanning membrane protein in the endoplasmic reticulum, participating in the process of autophagy." (PMID 33863396, 2021). "Autophagy induced by the pancreatitis-associated protein, vacuole membrane protein 1 (VMP1), cooperates with KrasG12D to promote PDAC initiation." (PMID 34063828, 2021). "Over the past decade, other disorders apart from pancreatitis have been reported to be associated with VMP1, such as cancers and inflammatory bowel disease." (PMID 32296305, 2020). "VMP1 mRNA encodes a transmembrane protein that we cloned in 2002 due to its extraordinary pancreatic activation during the acute phase of pancreatitis." (PMID 27833900, 2016). "Consequently, the current study was designed to begin filling this gap in knowledge by studying how the pancreatitis-associated protein VMP1, a key regulator of autophagy, cooperates with oncogenic KRAS to give rise to PanINs." (PMID 27415425, 2016). "The regulatory role of VMP1 in the pathogenesis of various diseases, including neurodegenerative disorders, hepatitis, cancer, and pancreatitis, has been well established." (PMID 40629421, 2025). "Using the tissue-specific transgenic mouse model ElaI-VMP1, which constitutively expresses VMP1 in pancreatic acinar cells, we previously demonstrated that VMP1 expression induced by pancreatitis triggers a protective pathway that we termed zymophagy." (PMID 40243995, 2025). "The VMP1 gene was discovered through the development of a copy DNA (cDNA) library of overexpressed genes in an experimental rat model of pancreatitis." (PMID 38612567, 2024). "In a normal pancreas, VMP1 expression is nearly undetectable, becoming activated under stress conditions such as pancreatitis, diabetes, or cancer transformation." (PMID 38612567, 2024). "Dysregulation of VMP1 has been observed in several pathological conditions, including neurodegenerative diseases such as Parkinson’s disease (PD), pancreatitis, hepatitis, and tumorogenesis, underscoring its potential as a therapeutic target." (PMID 39100095, 2024). "Previous studies of our laboratory identified VMP1 (NM_138839) as a novel autophagy-related protein in which its expression is induced in the human pancreas with pancreatitis and in experimental pancreatitis under the G-coupled receptor CCK-R hyperstimulation." (PMID 33816487, 2021). "Together, these results show that VMP1 mediates the selective autophagy of damaged mitochondria during experimental pancreatitis." (PMID 33816487, 2021). "We have identified a VMP1 mediating pathway in mitophagy, which selectively sequesters and degrades damaged mitochondria during the initial steps of experimental pancreatitis." (PMID 33816487, 2021). "In this study we demonstrate a novel role for vacuole membrane protein 1 (VMP1), a pancreatitis-associated protein critical for inducible autophagy, in the regulation of Kras-induced PDAC initiation." (PMID 27415425, 2016). "VMP1 is a transmembrane protein highly activated in acinar cells early during pancreatitis-induced autophagy, and it remains in the autophagosomal membrane." (PMID 22550490, 2012). "The in vivo gen expression of VMP1 in pancreas with pancreatitis correlates with morphological features resembling autophagy." (PMID 22550490, 2012). "For the first time, it was demonstrated that there is activation of the VMP1-autophagic pathway and a selective autophagy of secretory granules during human pancreatitis." (PMID 22550490, 2012).